CD47 (CD47 molecule)
Diseases named in the same sentence as CD47 in open-access papers (continued):
Sharing a sentence is not in itself a finding about the gene and the disease.
cancer (continued). "Since the binding of CD47 on cancer cells to SIRPα on macrophage results in inhibition of macrophage phagocytosis, bioinformatic analysis using TISIDB database suggests that TRAF2 expression is negatively correlated with macrophage abundance in LUSC." (PMID 39665172, 2025). "The upregulation of CD47 not only increases a cancer cell’s selfness but also leads to the blocking of cross-presentation by antigen-presenting cells (APCs)." (PMID 40356923, 2025). "Novel constructs such as diphtheria toxin-based bivalently immunotoxins, expressed through yeast-based systems, have also demonstrated high specificity and potent efficacy against CD47+ cancers with minimized off-target binding." (PMID 41179296, 2025). "Cancer cells often exploit CD47 to decrease phagocytic removal, prompting the development of therapies targeting CD47 to improve immune detection and elimination." (PMID 40255405, 2025). "While CD47 has been explored as a cancer target, its ubiquitous expression throughout the human body has led to off-target effects, such as anemia." (PMID 40136470, 2025). "Inhibiting QPCTL disrupts CD47 signaling, enhancing neutrophil-mediated cancer cell killing in vivo and offering a potential alternative to CD47-targeting antibodies." (PMID 40087690, 2025). "c‐47–SIRPα pathway is an innate immune checkpoint in cancer, and blocking the interaction of CD47–SIRPα amplifies the anticancer effects of neutrophils." (PMID 40979214, 2025). "CD47 is highly expressed in solid tumors and hematologic malignancies, and this overexpression correlates with poor prognosis in various cancers." (PMID 40013150, 2025). "This dual activation of both innate and adaptive immunities underscores the therapeutic potential of including the blockade of CD47 in comprehensive cancer management strategies." (PMID 41383500, 2025). "In cancer immunology, evidence suggests that SIRPα–CD47 interactions enhance cell-cell adhesion and T cell cytotoxicity against tumors." (PMID 41245087, 2025). "This interaction has been extensively studied, particularly in the context of cancer cells, which can upregulate CD47 to block immune-mediated phagocytic removal." (PMID 40255405, 2025). "CD47‐targeted NIR‐PIT has a dual effect on killing cancer cells directly and enhancing phagocytosis in a light dose‐dependent manner." (PMID 40385528, 2025). "SIRPα is widely studied as an inhibitory receptor on macrophages, which recognizes as a ligand of the cell surface molecule CD47, expressed mainly on myeloid cells and also upregulated on cancer cells." (PMID 40523887, 2025). "As expected, CD47 mRNA was highly abundant in all cancer entities evaluated and, interestingly, displayed the highest expression in EOC." (PMID 40402266, 2025). "Extensive research underscores ubiquitous overexpression of CD47 in a wide range of tumors, with its heightened expression levels prognosticating dismal survival outcomes for cancer patients." (PMID 40143965, 2025). "CD47 acts as an antiphagocytic receptor and anti-CD47 therapies have been tested in patients with cancer, using the humanized anti-CD47 antibody termed magrolimab." (PMID 41205263, 2025). "CD47, often referred to as the “don’t eat me” signal, is an immune checkpoint molecule that allows cancer cells to evade phagocytosis." (PMID 39857116, 2025). "H101 infection decreased the expression of CD47 in cancer cells, thereby promoting macrophages to phagocytose cancer cells." (PMID 40296909, 2025). "Since CD47 is miR-96-5p’s direct target, we investigated how it affects macrophages’ ability to engulf cancer cells." (PMID 41350707, 2025). "In the context of MM cancer cells upregulate CD47 to evade immune surveillance, exploiting this pathway to enhance their survival." (PMID 40013150, 2025). "Background/Objectives: Magrolimab (Magro) is a humanized naked anti-CD47 monoclonal antibody that blocks the SIRPα CD47 interaction, allowing macrophages to target and destroy cancer cells." (PMID 40361435, 2025).
cancer (continued). "Emerging research underscores the therapeutic potential of targeting the signal-regulatory protein alpha (SIRPα)-CD47 immune checkpoint in cancer treatment." (PMID 41402667, 2025). "CD47 is a surface receptor on cancer cell and delivers the “don’t eat me” signal by interacting with SIRPα on myeloid cells, while costimulatory molecules CD80 and CD86 participate in the regulation of antigen presentation and T cell activation." (PMID 40708945, 2025). "The immune checkpoint CD47 is highly upregulated in several cancers as an innate immune escape mechanism." (PMID 40402266, 2025). "This asks us to exercise caution and re-evaluate the rationale for using antibodies as a key to CD47-based cancer therapy." (PMID 41511354, 2025). "Immunotherapy methods that block the CD47-SIRPα signaling axis have shown promising preclinical activity, significantly inducing phagocytosis in various types of cancer." (PMID 40523887, 2025). "The interaction between CD47, overexpressed on many cancer cells, and SIRPα on phagocytes delivers a “don’t eat me” signal, inhibiting phagocytosis and facilitating immune evasion." (PMID 40396172, 2025). "This study offers novel insights into the potential repurposing of CGs for anti‐cancer applications within the framework of macrophage‐related immune response, and establishes a conceptual basis for the future clinical translation of CD47 antibody therapies." (PMID 40985476, 2025). "Initially identified as a marker of ovarian cancer, CD47 was later found to be ubiquitous in different mammalian cell types, leading to a paradigm shift in cancer immunotherapy." (PMID 39367479, 2025). "Overexpression of CD47 in various cancers promotes immune evasion and highlights its potential as therapeutic target." (PMID 41303525, 2025). "In recent years, CD47 has been recognized not only as a critical target in cancer therapy but also as a participant in the development of metabolic diseases through complex signaling pathways." (PMID 40630093, 2025). "c-MYC contributes to initiate and maintain tumorigenesis in many human cancers and regulates the antitumor immune response through CD47 and PD-L1, providing new insights into immunotherapies and epigenetic therapies." (PMID 41190324, 2025). "Many cancer cells overexpress CD47 to avoid immune clearance, making the CD47–SIRPα axis a promising target in cancer immunotherapy." (PMID 41303525, 2025). "Both CGs decreased the number of remaining cells at the nanomolar level, and the percentage of remaining cancer cells decreased dramatically when 50 nM ouabain or 200 nM digoxin was combined with CD47 antibody." (PMID 40985476, 2025). "This promotes interaction with CD47 on cancer cells, triggering the “don't eat me” signal and preventing cancer cell phagocytosis." (PMID 40547943, 2025). "Recent advancements in cancer immunotherapy have ushered in the era of immune checkpoint blockade, with newer targets such as CD47, LAG-3, TIM-3, TIGIT, and B7-H3 being explored in preclinical and clinical trials as potential therapeutic agents." (PMID 40087690, 2025). "Given CD47’s role in immune evasion, a MSLN-targeting approach was developed to block CD47-dependent escape mechanisms in cancer cells." (PMID 41335396, 2025). "The development of monoclonal antibodies targeting CD47 has shown encouraging results in enhancing antitumor immunity, highlighting the potential of these innate immune checkpoints as targets for cancer immunotherapy." (PMID 41243973, 2025). "Several approaches to inhibit CD47/SIRPα signaling are currently being tested in cancer, either specifically blocking CD47 or SIRPα with antibody-based or gene knockout approaches, as well as bispecific approaches that block both CD47 and SIRPα." (PMID 40082557, 2025). "Binders of the CD47 ECD are also in play in outside of cancer, such as in atherosclerosis, an idea previously validated to be feasible." (PMID 41511354, 2025).
cancer (continued). "CD47, a negative regulator of the macrophage scavenging receptor SIRPα, is often expressed on cancer cells, enabling evasion of cellular removal in certain cancers." (PMID 41007845, 2025). "The increased expression of CD47 on MHC-II+ cancer cells further promoted interactions with SIRPα on macrophages, to a greater extent than that observed in MHC-II− cancer cells." (PMID 41281745, 2025). "The myeloid-specific immune checkpoint regulator SIRPα is a receptor for CD47, which is expressed on both tumors and normal tissues and represents a promising target for cancer immunotherapy." (PMID 40136470, 2025). "Increasing evidence demonstrates that blocking the interaction between CD47 and SIRPα can enhance cancer cell clearance by macrophages, which is particularly relevant in SCLC, where TAMs are the dominant cell type in the TME." (PMID 40361334, 2025). "CD47 inhibitors have emerged as promising candidates in cancer immunotherapy by activating macrophage phagocytosis through CD47/SIRPα signal blockade and enhancing dendritic cell antigen presentation." (PMID 40652522, 2025). "Cancer cells, particularly cancer stem cells, often overexpress cluster of differentiation 47 (CD47)." (PMID 41179690, 2025). "Rather than signaling failure, these developments underscore the need for precision, context-specific applications, and adaptive trial designs to realize the durable therapeutic promise of CD47 blockade in cancer immunotherapy." (PMID 41179296, 2025). "A new nano-immunotherapy uses nanoparticles loaded with anticancer drugs and dual antibodies (e.g., against CD47 and PD-L1) to deliver drugs directly to cancer cells while enhancing both innate and adaptive immune responses and minimizing toxicities." (PMID 41471095, 2025). "In conclusion, Our study demonstrated that H101 acts synergistically to enhance the therapeutic efficacy of PD-1 blockade in cancer through suppressing CD47 signaling." (PMID 40296909, 2025). "The intervention with CD47 antibodies significantly increased the phagocytosis of cancer cells by macrophages compared with cancer cell lines treated with isotype control antibody IgG1." (PMID 40385528, 2025). "The presence of CD47 on cancer-cell-derived sEVs allow them to escape immune rejection and extends their lifetime in circulation." (PMID 39984653, 2025). "This metabolic reprogramming, coupled with CD47-mediated immune evasion, provides a dual survival advantage for therapy-resistant and recurrent cancer cells." (PMID 41163221, 2025). "Consideration of reasons accounting for the modest benefits realized by molecules that bind to the CD47 ECD in cancer, also known as Plan A, is provided." (PMID 41511354, 2025). "The SIRPα/CD47 axis serves as a critical immune checkpoint, inhibiting macrophage-mediated phagocytosis of cancer cells." (PMID 40136470, 2025). "CD47 is abundantly expressed on erythrocytes, platelets, and neurons, but cancer cells also express CD47 and evade phagocytosis by macrophages." (PMID 40940867, 2025). "Our results demonstrated that H101 infection induced downregulation of CD47 in infected cancer cells, which promoted macrophages to phagocytose cancer cells." (PMID 40296909, 2025). "CD47 is a checkpoint for phagocytosis in macrophages and a therapeutic target for several cancer types." (PMID 40143965, 2025). "covered the CD47 signals by depositing a thin film of iron oxide hydroxide on the surface of the isolated cancer cell‐derived EVs via a mild surface reaction while preserving their antigenic payload." (PMID 40600457, 2025). "For example, peptides designed to block the CD47-mediated ‘don’t eat me’ signal through CD47 targeting or its receptor SIRPα on macrophages can enhance phagocytosis of cancer cells." (PMID 40564134, 2025). "A549 and H1975‐bearing BALB/c nude mouse models were used to test the anti‐cancer effect of ouabain co‐administration with antibody targeting CD47." (PMID 40985476, 2025).
cancer (continued). "The first-in-class IgG4 CD47-targeting mAb magrolimab, followed by others, demonstrated robust anti-cancer activity in patients with hematologic and solid cancers." (PMID 40402266, 2025). "Upregulation of CD47 in cancer cells can allow them to evade phagocytosis, and this process is harnessed by cancer cells to induce immune suppression." (PMID 41354057, 2025). "CD47 is broadly expressed on normal cells but is frequently upregulated in cancer, including hematologic malignancies and solid tumors, where it engages signal regulatory protein alpha (SIRPα) on macrophages and dendritic cells (DCs)." (PMID 41179296, 2025). "An increasing number of CD47 inhibitors are being used in cancer treatment and have entered clinical trials." (PMID 41341383, 2025). "This commentary aims to contextualize recent clinical outcomes, dissect mechanistic insights, refine their clinical translation, and outline future directions for advancing CD47 blockade into durable, safe, and effective cancer immunotherapies." (PMID 41179296, 2025). "Expression levels of both CD24 and CD47 in the cancer population were higher than those in the normal population." (PMID 41354057, 2025). "Notable downregulated genes included Mki67, Ccn1, Muc1, Atf3, Ntrk2, Arid5b, Igf1r, Igf2bp2, Cd47, and Cd37 (oncogenic function) and integrin-related genes, Itga7, Itga11, Itgam and Notch1 (cancer stem cell markers)." (PMID 39946195, 2025). "Cancer cells upregulate CD47 expression to promote immune escape through activating the “don’t eat me” signal via interactions with signal regulatory protein α (SIRPα) on macrophages." (PMID 40578556, 2025). "Recent studies have highlighted the role of the SIRPα-CD47 axis in cancer immune suppression, revealing its complex dual roles in immune evasion and treatment." (PMID 40016734, 2025). "Strategies that combine immune checkpoint PD-1/PD-L1 blockade with innate immune checkpoint CD47/SIRPα blockade exhibit potential in cancer immunotherapy." (PMID 40296909, 2025). "SREBP1 is the downstream transcription factor of SMYD3 that regulates CD47 expression in ccRCC, and CD47 is well characterized as an inhibitory checkpoint target expressed on the surface of cancer cells." (PMID 40548645, 2025). "Various transcription factors can upregulate CD47 on the surface of cancer cells, such as MYC, nuclear factor kappa B (NFκB), signal transducer and activators of transcription 3 (STAT3), and hypoxia-inducible factor-1(HIF-1)." (PMID 40835598, 2025). "In a recurrent GBM model, the authors demonstrated how the combination of PA1094T and anti-CD47 Ab significantly enhanced cancer cells phagocytosis and remodeled the TME." (PMID 40867316, 2025). "Several other CD47-blocking antibodies are currently in various stages of clinical trials targeting different types of cancer." (PMID 41300494, 2025). "CD47 is highly expressed on cancer cells and triggers an anti-phagocytic “don’t eat me” signal when bound by the inhibitory signal regulatory protein α (SIRPα) expressed on macrophages." (PMID 40078999, 2025). "EGFR mutant NSCLC tumors evade macrophage phagocytosis via activating the AKT/NF‐κB and ERK/c‐Myc signaling pathways to increase CD47 expression, which acts as a signal of “don't eat me,” preventing macrophages from phagocytosing cancer cells." (PMID 40859900, 2025). "CD47 is an immunoglobulin broadly overexpressed on the surface of cancer cells; CD47 inhibits macrophage‐mediated phagocytosis through binding to SIRPα on phagocytes." (PMID 41354057, 2025). "The membrane proteins such as CD44 and CD47 were examined by Western blotting since they play a crucial role in cancer metastasis." (PMID 40274835, 2025). "The present study offers a comprehensive meta‐analysis of CD47 expression across 11 cancer types, involving 4019 patients from seven countries." (PMID 40765033, 2025).
cancer (continued). "The IgA2 designs were further shown to bind FcaRI and to engage PMNs for directed killing of HER2-expressing cancer cell lines, which was enhanced by CD47 blockade." (PMID 40041621, 2025). "The high expression level of CD47 and activation of the CD47-SIRPα pathway are correlated with a low survival rate in cancer patients." (PMID 40574837, 2025). "As an immune checkpoint in the myeloid-specific system, CD47 effectively protects cancer cells from phagocytosis by binding to SIRPα on phagocytic cells, thereby inhibiting the phagocytic activity of macrophages in the immune system[33,]." (PMID 40129966, 2025). "Cancer cells preferentially express CD47 as a ‘don’t eat me signal’, which protects them from macrophage-mediated phagocytosis." (PMID 39039207, 2024). "This evidence collectively suggests the potential of 47VHH1H4 as a potent CD47-blocking agent for cancer immunotherapy." (PMID 38247566, 2024). "The SIRPα/CD47 signaling axis has emerged as a promising therapeutic target in cancer immunotherapy." (PMID 39160226, 2024). "Since SIPRα can block CD47, a tumor antigen related to cancer immunotherapy, SIPRα-loaded exosomes can target cancer cells for immunotherapy, and the loaded doxorubicin increases the anticancer effect." (PMID 38556545, 2024). "Cancer cells can evade clearance by macrophages through overexpression of antiphagocytic surface proteins including CD47, programmed cell death ligand 1 (PD-L1), the beta-2 microglobulin subunit of the major histocompatibility class I complex (B2M), and CD24." (PMID 38702326, 2024). "The current development on the first-generation anti-CD47 antibody magrolimab highlights challenges in targeting the CD47-SIRPA axis for cancer immunotherapy." (PMID 38920727, 2024). "Several CD47 blocking antibodies are in clinical trials to harness the immune system and treat cancer." (PMID 38362603, 2024). "The earlier clinical application of the SIRPα-CD47 interaction in cancer therapy has shown promise, primarily utilizing anti-CD47 monoclonal antibodies to block the CD47 “don’t eat me” signal." (PMID 38881902, 2024). "As Tug1 inhibits the phagocytosis function of macrophages toward cancer cells by promoting Cd47 expression, we further used the ENCORI/starBase to predict the potential binding sites of miRNAs in the 3′UTR of Cd47." (PMID 38981064, 2024). "Our results underscore the potential of the engineered anti-CD47 nanobody as a promising candidate for cancer immunotherapy." (PMID 38247566, 2024). "Piecing it all together due to versatile factors that have an impact on CD47 expression, there are many possible approaches to blocking its function in cancer cells." (PMID 38892394, 2024). "Much progress has been made in targeting CD47 for cancer immunotherapy in solid tumors (STs) and hematological malignancies." (PMID 39795582, 2024). "This analysis of the NCI GDC database supports our previous findings and indicates that the CD36/CD47 dual marker can be broadly used to select patients for VT1021 by cancer indication and progression." (PMID 39627379, 2024). "The emergence of anti-CD47 therapies aimed at impeding CD47 interaction with SIRPα to improve macrophage-mediated cancer cell clearance has attracted much attention in recent years, with monoclonal antibodies in clinical trials." (PMID 39138571, 2024). "CD47 is a cell surface protein expressed on cancer cells that interacts with SIRPα on macrophages, delivering a “don’t eat me” signal and inhibiting phagocytosis." (PMID 39040441, 2024). "Magrolimab is a humanized IgG4 monoclonal antibody to CD47; by binding CD47, which is an anti-phagocytic protein, magrolimab enhances the macrocytic phagocytosis of cancer cells." (PMID 39200232, 2024). "Despite the considerable enthusiasm for targeting CD47 for cancer immunotherapy, remarkably, we know very little about transcriptional regulation of the CD47 gene." (PMID 38183060, 2024).